CD38 (CD38 molecule)
Diseases named in the same sentence as CD38 in open-access papers (continued):
Sharing a sentence is not in itself a finding about the gene and the disease.
infection (continued). "Cluster 10 was also found to expand in the first infection but was exceeded by cluster 11, which was similarly high for CD38 but otherwise transcriptionally distinct." (PMID 40214640, 2025). "We first monitored by flow cytometry lymphocyte proliferation using carboxyfluorescein succinimidyl ester (CFSE) dilution assay, as well as lymphocyte activation based on the expression of surface markers CD69, CD25, HLA-DR, and CD38 on day 6 post-infection." (PMID 40162896, 2025). "Coexpression of CD38 and PD1 on CD8+ T cells has been reported previously to be associated with higher viral load and T‐cell hyperactivation at the site of infection in severe influenza disease." (PMID 39971320, 2025). "Higher levels of B regulatory cells (B regs, CD24 high/CD38 high) were detected in the early phase of the MPXV infection (T0 = 3.0% vs. T2 = 1.1%, p = 0.017)." (PMID 40005722, 2025). "Significantly higher CD38 expression was only observed on day 2 after infection in the Delta group compared to the Ad5 and LAV animals." (PMID 41390777, 2025). "Early in the infection, there is typically an increase in the proportion of highly activated (CD38+) and proliferating (Ki-67+) CCR5+CD4+ T cells." (PMID 40141240, 2025). "CD38, the most reliable surrogate marker for T cell immune activation, was significantly upregulated at the early stage of infection (day 1) in a subset of both CD19+ B cells and CD4+ T lymphocytes." (PMID 40733503, 2025). "Activation markers including HLA-DR and CD38 for immune cells provide information about KTRs’ reaction to infection or cancer, and the combination of CD38 and HLA-DR proved to help detect activated T cells." (PMID 40568581, 2025). "Anti-CD38-based therapies have significantly improved RRMM outcomes, but are associated with increased infection risks because of immunosuppressive effects." (PMID 40786241, 2025). "As infection progressed, CD38− TR-AM numbers decreased, while CD38+ TR-AMs and the newly recruited moAMs rose in prevalence." (PMID 39070650, 2024). "In the later stages of infection, these CD38+ AM subsets emerged as the dominant infected host AM populations, demonstrating enhanced capacity to restrict Mtb’s growth." (PMID 39070650, 2024). "This assumption fits well with a case report of an HIV-positive woman who showed a dramatic increase in the frequency of CD38+HLA-DR+ CD8+ T cells approximately two months after mpox infection." (PMID 38400115, 2024). "Next, we asked if CD38 expression was also increased on virus-specific CD8+ T cells upon acute infection at an early time point." (PMID 38954588, 2024). "In vivo antigen-activated human T cells have been shown to be identified by a CD38 bright, HLA-DR+ phenotype after infection." (PMID 38533498, 2024). "In certain infections, CD38+CD8+T cells undergo a rapid increase after the infection once the immune control of acute phase is achieved." (PMID 39726780, 2024). "T-bet, RUNX3, and EOMES are attenuated in CD8 + CD38 + T cells from SLE patients, resulting in a decrease in CD8 T cell-mediated cytotoxicity and an increase in susceptibility to infection." (PMID 38650001, 2024). "CD38 is a pleiotropic, ubiquitously expressed receptor and ectoenzyme that is robustly induced during inflammation and infection and is generally considered a drug target in aging and metabolic diseases." (PMID 38318168, 2024). "In a resting state, a higher percentage of APN−/− AMs were CD38+ and lower percentage were Egr2+ when compared to WT, while upon infection with A. fumigatus, percentages of both CD38+Egr2− and CD38-Egr2+ cells increased." (PMID 38979340, 2024). "Moreover, in patients with systemic lupus erythematodes (SLE) and increased susceptibility to infections, it was shown that CD38 overexpression in CD8+ T cells leads to mitochondrial dysfunctionality accompanied by restricted cytokine production, which could be improved by CD38i treatment." (PMID 38954588, 2024).
infection (continued). "As infection progressed, we observed a phenotypic shift in AMs, with CD38+ monocyte-derived AMs (moAMs) and a subset of tissue-resident AMs (TR-AMs) emerging as significant controllers of bacterial growth." (PMID 39070650, 2024). "We also saw differences between the two groups, with CCR2 more highly expressed on CD8+ T cells in naïve participants, while CD57 and CD38 were more highly expressed in those with a history of previous infection." (PMID 37604803, 2023). "It is also possible that the gene ratio CD16/CD38 is more sensitive to other factors, such as the type of infection." (PMID 38053180, 2023). "The frequency of HLA-DR+CD38+CD4+ T cells significantly increased after breakthrough infection compared to that before infection in heterologous booster individuals." (PMID 38140668, 2023). "Tr1 cells also showed significant activation during infection, with marked upregulation of CD38 and ICOS during infection." (PMID 37968278, 2023). "CD38 is widely expressed in various immunocytes membranes and involved in the natural immune response against infection." (PMID 36998049, 2023). "Future clonality studies involving the LN would give more clarity to this standardization, as well as possibly incorporating markers such as CXCR3, ICOS, CD38 or HLA‐DR to identify acute specific cTfh cells after infection or vaccination." (PMID 36825370, 2023). "Of note, at SVR12, the HIV-HCV co-infected subjects displayed significantly higher CD69 + γδ + (p = 0.02), as well as CD38 + γδ + T-cells (p = 0.003) as compared to individuals with HCV mono-infection." (PMID 35893661, 2022). "In contrast, in vitro infection with R5 HIV-1 was only achieved in CD34+CD38+ progenitors and to a significantly lower extent compared to X4." (PMID 36230931, 2022). "Altogether, our data support CD38-TAM as an accurate marker of infection resolution independently of sputum bacterial load." (PMID 35492319, 2022). "When compared with that in uninfected animals, expression of CD38 increased significantly in both models shortly after infection." (PMID 36010615, 2022). "Although highly expressed on malignant myeloma cells, CD38 is also expressed albeit at lower levels on natural killer (NK) cells, monocytes and some T-cells during infection." (PMID 35199207, 2022). "During the first year of infection, the frequency of activated CD38+ or CD69+ iNKT cells strongly correlated with alanine transaminase levels with particularly pronounced correlations in spontaneously resolving patients." (PMID 34905514, 2022). "CD38 was more highly expressed on monocytes from the parasitic model during the early phase of infection, thus describing inflammatory Ly6Chi before transitioning to Ly6Clo cells." (PMID 36010615, 2022). "From this result, CD38 can be considered as the factor contributing to the expression of TLR9 after PPV infection." (PMID 35746608, 2022). "An opposing trend—increase during acute infection—was observed for both the CD45RA+CD38+CD27+ and CD45RA+CD127−CD27+ populations, reminiscent of gradual differentiation into stem cell memory (TSCM) and effector memory (TEMRA), respectively." (PMID 35215797, 2022). "Lastly, as the expression of activation markers (CD38, HLA-DR, Ki-67 or PD-1) on antigen-specific T-cells is indicative of active infection, we defined the expression of these markers on SARS-CoV-2-responding CD4 T-cells." (PMID 34140294, 2022). "The CD38 is a multifunctional protein that functions as an enzyme and studies on animals indicate that CD38 expression protects against infection." (PMID 36142442, 2022). "While number of total CD19+ B cells was unchanged over time, percentage of CD27+ CD38+ plasmablasts from total CD19+ B cells increased from approximately 0.75% at baseline to more than 15% on day 7 after infection." (PMID 34169553, 2022). "The relative mRNA levels of IFN-α and CD38 in PK-15 cells were analyzed at multiple post-infection times." (PMID 35746608, 2022).
infection (continued). "In summary, ROS-production as well as the expression of CD38 characterizes the true proinflammatory phenotype of Ly6Chi monocytes in both infection models." (PMID 36010615, 2022). "Whilst a role for CD38 in supporting the trafficking of immune cells during infection-induced inflammation has been established, the association of CD38 with the process of T cell trans-endothelial migration across the BBB is yet to be elucidated." (PMID 36294327, 2022). "The most striking finding regarding the iNKT cell phenotype in different infection outcomes was the downregulation of CD38 and CD69 in the context of HCV resolution." (PMID 34905514, 2022). "It has been reported that CD38 expression in immune cells is increased in response to infection and inflammation, which subsequently induce inflammatory response." (PMID 36426217, 2022). "High levels of human virus-specific CD38+ CD4+ T cells have been reported to be transiently present during acute presentations also of other infections such as: CMV or EBV infections." (PMID 33419040, 2021). "One month after the onset of symptoms, HLA-DR/CD38/PD-1 expression drastically decreased compared to the early stage of the infection." (PMID 33617602, 2021). "Shifts in CD38 expression have also been observed during infection, although reports of corroborating NAD+ concentrations or altered NAD+ turnover are scarce." (PMID 34485381, 2021). "Like CD38, CD157 is implicated in an array of immunomodulatory processes, notably the migration, adhesion and extravasation of leukocytes for recruitment to infection sites during immune activation and is also a marker for myeloid cell differentiation." (PMID 34485381, 2021). "CD38 is a glycoprotein widely expressed in cells from the immune system, and animal studies indicate that it confers protection against infection by several bacterial and parasitic pathogens, suggesting its role on regulation of inflammatory protein response." (PMID 34512620, 2021). "An increased activity of the metabolic genes at the mid-log phase was also reported in phage CD38–2 infection of R20291." (PMID 34835068, 2021). "Compared with the asymptomatic infection and uninfected individuals, we observed a higher frequency of dysfunctional CD38+ HLA-DR- CD8+ T cells subpopulation during the symptomatic phase." (PMID 34669281, 2021). "This importance is also demonstrated in CD38−/− mice which are sensitized to infection by many bacterial pathogens including Mycobacterium and Listeria monocytogenes due to tempered neutrophil recruitment and inflammatory response." (PMID 34485381, 2021). "Ratios of CD38+ HLA-DR– CD4+ (P = 0.0027)/CD8+ (P = 0.0373) T-cell subsets in the SS phase were significantly higher than in SN before infection." (PMID 34349746, 2021). "The high levels of CD38 on HIV-infected cells were due to a combination of both selecting CD38high cells for infection and further CD38 upregulation." (PMID 33910003, 2021). "We expected similar results for HLA-DR as for CD38 expression, as it is known that in most infections there is a simultaneous increase in the expression of these two markers s." (PMID 33419040, 2021). "Antigen-specific CD8+ T cells, particularly in the early stages of infection, express CD38, HLA-DR, KI-67 and PD-1." (PMID 33575657, 2021). "CD38, an activation and endothelial-adhesion marker, was upregulated across diverse immune cells during active infection, indicative of widespread anti-viral responses." (PMID 34867943, 2021). "The observation that even 70 days after infection T cells are expressing HLA‐DR and CD38 speaks for their sustained SARS‐CoV‐2‐dependent activation." (PMID 33128792, 2021). "Early initiation of antiretroviral therapy during the acute infection phase (Fiebig I/II) can reduce activation markers (percentage of mucosal and peripheral CD38+/HLA-DR+/CD8+ T cells) to the levels observed in uninfected individuals." (PMID 33820568, 2021).
infection (continued). "Although previous studies of KSHV infection in tonsil-derived B lymphocytes have shown the acquisition of plasmablast-like features at later timepoints post-infection, the CD38 high plasmablast lineage is a minor proportion of our infected cultures at 3 dpi." (PMID 33075105, 2020). "CD14, CD38, and Abca1 “triple positive” (TP) cells had not only the highest infection rates and bacterial loads, but also a strong interferon-γ signature and nitric oxide synthetase-2 production indicating recognition by T cells." (PMID 32544188, 2020). "A study in mice with Listeria monocytogenes infection has shown that upregulation of CD38 on neutrophils and macrophages is essential for their recruitment to the site of infection and efficient pathogen clearance." (PMID 32709019, 2020). "CD38 appears to be essential for both of these processes, as deletion of CD38 in mouse impairs the recruitment of immune cell from blood to sites of infection or tissue injury." (PMID 33329591, 2020). "The role of CD38 during infection-induced inflammation has been the focus of substantial study, revealing a supporting role for CD38 during inflammation." (PMID 33329591, 2020). "The aim of the present review is to provide an updated overview on the diversity of functions mediated by CD38 in the context of the host defense to infection." (PMID 31963337, 2020). "The CD38+/CD14+ cells were the main cell population that expressed high levels of ABCA1 after infection." (PMID 32544188, 2020). "Because of its abundant expression in immune cells, several studies have focused on the roles of CD38 in the immune response to infection." (PMID 31963337, 2020). "Altogether, the observations in animal models indicate the importance of CD38 in the control of infection, raising its potential interest as a target for host-directed therapy against infection." (PMID 31963337, 2020). "We found that Ad-PTEN infection significantly enhanced expression of the PTEN protein in the lung tissue of asthmatic mice, and caused a marked reduction in the expression of the CD38 protein." (PMID 32889801, 2020). "Studies in animal models indicate that CD38 functional expression confers protection against infection by several bacterial and parasitic pathogens." (PMID 31963337, 2020). "In many patients, CD4 and CD8 T cell proliferation (measured by KI67 increase) and activation (detected by CD38 and HLA-DR coexpression) were consistent with antiviral responses observed in other infections." (PMID 32669297, 2020). "Of note, many patients undergoing anti-CD38-based immunotherapy are in relapsed or refractory phases of the disease and have been heavily treated, which implies that immunosuppression derived from previous lines of treatment could influence the risk of infection." (PMID 31963337, 2020). "Following infection, MAIT cell supernatants exhibited similar effects as MAIT cells from vaccinated macaques, although levels of CD38 expressing cells declined somewhat and loss of IgD expression was not as great." (PMID 32572140, 2020). "So far, it is known that CD38 expression is robustly induced in immune cells after activation and regulates infection-induced inflammatory processes, from cell recruitment to induction of adaptative immune responses." (PMID 33329591, 2020). "Western blot analysis confirmed that infection of Ad-CD38 shRNA markedly decreased the protein expression of CD38 in ASM cells." (PMID 32889801, 2020). "This review integrates the current knowledge on the diversity of functions mediated by CD38 in the host defense to infection." (PMID 31963337, 2020). "The presence of activated T cells is associated with increased susceptibility to infection; in particular, activation phenotypes of CD4+ T cells co-expressing the markers HLA-DR and CD38 and HLA-DR+CD38- cells are preferentially infected by HIV-1." (PMID 31550271, 2019).
infection (continued). "In the LN, the expression levels of CD38 and PD-L2 were significantly upregulated in chronically-infected macaques compared to pre-infection levels." (PMID 30941141, 2019). "Taken together, expression of CD38 on immune cells appears to play a role in the immune system, particularly in the context of infection." (PMID 31214171, 2019). "Studies indicated that CD38−/− mice have an impaired innate immunity including ineffective recruitment of neutrophils and monocytes towards sites of infection." (PMID 30915370, 2019). "All the differences above showed that the CD38−/− mice have suffered a more serious LPS-induced infection than the WT mice." (PMID 30915370, 2019). "CD38 is also an emerging therapeutic target under conditions in which metabolism is altered including infection, aging, and tumorigenesis." (PMID 31214171, 2019). "Early in the infection (∼d10), the frequency of CD38+HLA-DR+CD8+ T cells in the recovery group reached a mean of 26.6% (CI 95%: 15.4–37.8% at the earliest time-point), then gradually declined (∼d14–d18) to 10.3% (CI 95%: 3.8–16.8%) as patients recovered." (PMID 29483513, 2018). "From studies in dendritic cells, neutrophils, and monocytes, CD38 is known to be essential for trafficking and chemotaxis to sites of infection." (PMID 30042766, 2018). "Consistent with other studies, during acute infection stage, the percentages of CD38 and HLA-DR coexpression on CD4+ T cells was negatively correlated with CD4+ T cell count (r = −0.34, p = 0.08) and positively correlated with pVL (r = 0.88, p = 0.03)." (PMID 29636753, 2018). "Additional analysis of surface markers revealed no substantial differences in the expression of additional activation markers or tissue-homing markers between CD38+Ki67+and CD38−Ki67− cells at the peak of infection." (PMID 29343684, 2018). "Absolute cell count and phenotyping of splenic YFV-specific CD8+ T cells showed that these cells mostly expressed HLA-DR and CD38 at day 20 post infection." (PMID 30487575, 2018). "Other genes in this network associated with immunity and infection were toll-interleukin 1 receptor (TIR) domain containing adaptor protein, CD38 molecule, CD48 molecule, CD81 molecule, inducible T-cell co-stimulator ligand." (PMID 29302351, 2017). "Prior to infection, CD38+ and CD38- CD8+ T cells had the same ability to degranulate, whereas post-infection CD38+ CD8+ T cells had a higher degranulation compared to CD38- CD8+ T cells." (PMID 27930660, 2016). "Although infection led to significant changes in the phenotype of both CD38+ and CD38- CD4+ T cell subsets during infection, there was a marked increase in CD45RA expression and decrease in Ki67 expression within CD38+ but not CD38- CD4+ T cells." (PMID 27662621, 2016). "We found similar expression of granzyme B and perforin in CD38+ and CD38- CD8+ T cells before infection." (PMID 27930660, 2016). "Accordingly, we measured the expression of Ki67 and Bcl2 by flow cytometry within CD38+ and CD38- CD4+ T cells circulating in the healthy volunteers prior to infection, as well as at peak of infection seven days after inoculation." (PMID 27662621, 2016). "Effector T cell populations expanding in response to infection or immunization have been shown to express high levels of CD38 and the proliferation marker Ki67 but low levels of the anti-apoptotic molecule Bcl2." (PMID 27662621, 2016). "In both cell subsets, there was an overall decrease in Bcl2 expression at 7 days post infection compared to prior to infection, but to a greater extent for CD38+ CD4+ T cells." (PMID 27662621, 2016). "All CD38+ CD4+ T cells isolated from healthy volunteers either prior to infection, or during experimental malaria infection, displayed similar features clearly distinguishing them from CD38- CD4+ T cells." (PMID 27662621, 2016).